EGFR (epidermal growth factor receptor)
Diseases named in the same sentence as EGFR in open-access papers (continued):
Sharing a sentence is not in itself a finding about the gene and the disease.
lung cancer (continued). "Perhaps the best example of this is the oncogenic mutation of Epidermal Growth Factor (EGFR) in lung cancers." (PMID 35061724, 2022). "ddPCR showed 53% clinical sensitivity in the detection of EGFR mutations in plasma cell-free DNA from patients with lung cancer." (PMID 35202431, 2022). "Eighteen females and nine males harbored EGFR mutations, and more female lung cancer patients harbored EGFR mutations than males (P < 0.001)." (PMID 34170380, 2022). "More than 60% of NSCLCs have been identified to have overexpression of EGFR, and in Canada, EGFR mutations are identified in approximately 15% of all lung cancer cases." (PMID 36290844, 2022). "Double mutations of G719A and L833V in EGFR rarely coexist in lung cancer, and few published studies have detailed the clinical profiles." (PMID 35984165, 2022). "Another study revealed that acquired resistance of EGFR-mutated lung cancer to TKI treatment promoted PARP inhibitor sensitivity." (PMID 35643428, 2022). "EGFR is closely associated with strong proliferation ability, poor differentiation ability, high lymph node metastasis rate, and poor prognosis of lung cancer." (PMID 35706930, 2022). "The overall mutation rate of the EGFR gene in lung cancer patients of Qujing origin was 47.22%, 19-del was 21.32%, and L858R was 33.09%." (PMID 35606799, 2022). "Lung cancer that is driven by mutations in the epidermal growth factor receptor (EGFR) is currently treated with tyrosine kinase inhibitors (TKIs)." (PMID 36010935, 2022). "Osimertinib is currently the first line drug recommended by National Comprehensive Cancer Network (NCCN) guidelines against lung cancer harboring the EGFR TKI-sensitive mutation and acquired EGFR T790M resistance mutation." (PMID 35494059, 2022). "EGFR-TKI targeted therapy is one of the most effective treatments for lung cancer patients harboring EGFR activating mutations." (PMID 36203195, 2022). "Although they analysed 102 EGFR-mutated lung cancer patients, only 18 non- EGFR Q787Q polymorphism cases were included in the survival analysis of EGFR mutants because of the high prevalence of the EGFR Q787Q polymorphism." (PMID 35387120, 2022). "Epidermal growth factor receptor (EGFR) tyrosine kinase inhibitors (TKIs) are widely used for the treatment of EGFR mutation positive advanced nonsmall cell lung cancer (NSCLC); however, acquired resistance is known to develop during these treatments." (PMID 35960133, 2022). "More specifically, elevated RhoB expression in EGFR-mutated lung cancer tumors was associated with poor response to EGFR-tyrosine kinase inhibitors." (PMID 35884561, 2022). "Osimertinib is a mutant-selective EGFR-TKI that targets treatment-naïve EGFR mutant lung cancers and cancers that acquire a gatekeeper EGFR T790M mutation after treatment with EGFR-TKIs6,7." (PMID 36153311, 2022). "Epidermal growth factor receptor tyrosine kinase inhibitors (EGFR TKIs) are widely used in EGFR mutation positive advanced nonsmall cell lung cancer (NSCLC)." (PMID 35960133, 2022). "EGFR is a transmembrane receptor tyrosine kinase whose overexpression is linked to the development of lung cancer." (PMID 36263432, 2022). "To detect these EGFR gene mutations and select the optimal treatment, we performed a total of 104 liquid biopsies in patients diagnosed with lung cancer in our daily clinical practice." (PMID 36497340, 2022). "Primary lung cancer cells bearing activating epidermal growth factor receptor (EGFR) mutations enter a reversible dormant state under hypoxic conditions, resulting in resistance to EGFR tyrosine kinase inhibitor treatment and irradiation." (PMID 35158815, 2022).
lung cancer (continued). "Herein, we characterize the landscape and prognostic significance of the T cell receptor (TCR) repertoire of early-stage non–small cell lung cancer (NSCLC) for patients with an epidermal growth factor receptor (EGFR) mutation." (PMID 35014626, 2022). "This EQA demonstrated the feasility of delivering a large worldwide EQA assessing accuracy and reporting of cfDNA testing for EGFR variants in lung cancer." (PMID 35820813, 2022). "The frequency of EGFR gene mutation was significantly different among the lung cancer patients of the various races or ethnic groups." (PMID 35606799, 2022). "With the improvement of early lung cancer scanning, the proportion of surgical lung cancer patients is increasing, and EGFR‐mutate patients are the major part of them especially in Asia." (PMID 35023616, 2022). "We also detected higher levels of CLEC11A proteins in lung cancer cell lines harboring an endogenous EGFR kinase domain mutation." (PMID 35267664, 2022). "The treatment of EGFR-mutated lung cancer cell lines with erlotinib enriched then stem-like cells with stem-like cell potential through EGFR-dependent activation of NOTCH3." (PMID 35584089, 2022). "Gefitinib (IressaTM, ZD-1839) was the first EGFR tyrosine kinase inhibitor (TKI) that was approved by the FDA, in 2003, to be used as the first line of treatment for lung cancer with mutated EGFR." (PMID 35164092, 2022). "Survival and treatments administered differ for distinct types of lung cancer, especially those involving driver gene mutations such as epidermal growth factor receptor mutation in lung adenocarcinoma." (PMID 35626156, 2022). "The lung cancer patients with different EGFR gene mutations can display different sensitivities to EGFR-TKIs." (PMID 35606799, 2022). "Irrespective of the timing of the occurrence of mutations, analysis of EGFR mutations has been a crucial step for the application of tyrosine-kinase-inhibitor (TKI)-based targeted therapy in patients with lung cancer harboring EGFR mutations." (PMID 35740676, 2022). "In lung cancer cells, LL-37 upregulates the phosphorylation of EGFR and causes a subsequent activation of the Ras/MAPK cascade." (PMID 35039485, 2022). "In lung cancer treatment, the initial clinical response is satisfactory but eventually resistance is developed due the mutation in EGFR (T790M), MET gene amplification, and the activation of NF- κB and TGF-β." (PMID 36457709, 2022). "We simultaneously generated two cancer cell lines resistant to EGFR-TKI gefitinib using two lung cancer cell lines with the same EGFR mutation." (PMID 35326664, 2022). "This retrospective cohort study consecutively enrolled patients of EGFR‐mutated non‐small cell lung cancer treated with osimertinib." (PMID 35434933, 2022). "About 80% of lung cancers are non-small cell lung cancers (NSCLCs), and epidermal growth factor receptor (EGFR) gene mutations are considered to prompt NSCLC development." (PMID 35370706, 2022). "Upregulation of EGFL7 activates NOTCH signaling in lung cancer cells, which slows down the decrease of c-Myc caused by EGFR inhibition, thereby helping the survival of cancer cells." (PMID 36309484, 2022). "Recent studies have found co-occurring genomic alterations were common in EGFR-mutated lung cancers." (PMID 35643428, 2022). "The experiment found that EGFR gene mutations are crucial in the treatment of lung cancer through noninvasive radiomic features." (PMID 36593900, 2022). "For patients with epidermal growth factor receptor (EGFR)-mutated lung cancer who undergo surgery, adjuvant tyrosine kinase inhibitor (TKI) therapy other than osimertinib is an alternative option." (PMID 35360423, 2022). "The ERK pathway is active in the majority of human lung cancers, especially in lung adenocarcinomas, because its upstream cues Ras and EGFR are frequently mutated." (PMID 35819844, 2022).
lung cancer (continued). "In this study, the 15 patients carrying EGFR-activating mutations were selected to receive EGFR-TKI therapy according to the guidelines for the clinical use of targeted drugs in lung cancer patients." (PMID 36376325, 2022). "Multi-center research indicated that the overall mutation rate of the EGFR gene in the Asia–Pacific region lung cancer patients was approximately 39.6%." (PMID 35606799, 2022). "First of all, KRAS and EGFR mutations have profound effects on the treatment and prognosis of lung cancer patients." (PMID 35392225, 2022). "Although EGFR and KRAS mutations typically occur in a mutually exclusive fashion in lung cancer; anecdotal reports show evidence of co-occurrence of KRAS and EGFR mutations in lung cancer patients." (PMID 35251972, 2022). "ERBB2 exon 16 skipping is also reported to be another mechanism of TKI resistance in EGFR-mutated patients with lung cancer, in addition to its role in other solid malignancies as an oncogenic driver." (PMID 35463314, 2022). "E709K is a mutation in EGFR exon 18 responsible for lung cancer cell resistance to gefitinib, erlotinib, AZD9291, and CO1686100." (PMID 35977996, 2022). "Gefitinib is currently used as a first-line treatment for lung cancer patients harbouring EGFR mutations." (PMID 35902569, 2022). "Specific miRNAs, such as miRNA-432-5p, promote resistance against EGFR inhibitors, while miRNA-27b can cause lung cancer chemo-resistance to retreat by down-regulating Snail1-mediated suppression of EMT." (PMID 35885514, 2022). "Alterations to the EGFR (epidermal growth factor receptor) gene, which primarily occur in the axon 18–21 position, have been linked to a variety of cancers, including ovarian, breast, colon, and lung cancer." (PMID 36457709, 2022). "It was worth noting that the frequency of EGFR gene G719X single-mutation and G719X + S768I compound double mutation in the lung cancer patients in the coal-producing areas was relatively high." (PMID 35606799, 2022). "Over the past decade, targeted therapy has become the mainstay of therapeutic regimens in lung cancer, especially EGFR‐mutated type." (PMID 35543090, 2022). "Activation of SALL4 in EGFR mutated lung cancer cells resulted in spheroid formation and expression of stem cell factor CD44." (PMID 36010677, 2022). "The role of EGFR in lung cancer is well described with numerous activating mutations that result in phosphorylation and tyrosine kinase inhibitors that target EGFR." (PMID 36054194, 2022). "Gefitinib, a well-known epidermal growth factor receptor (EGFR) tyrosine kinase inhibitor for the targeted therapy of lung cancer, induces autophagy in association with drug resistance." (PMID 38933121, 2022). "The presence of activating epidermal growth factor receptor (EGFR) mutations in patients with lung cancer correlates to improved response to EGFR-tyrosine kinase inhibitors." (PMID 36376325, 2022). "Both amplification and mutation of EGFR are frequently observed in lung cancers, which lead to the overactivation of the EGFR singling pathway." (PMID 35016696, 2022). "Circulating cell free DNA (cfDNA) testing of plasma for EGFR somatic variants in lung cancer patients is being widely implemented and with any new service, external quality assessment (EQA) is required to ensure patient safety." (PMID 35820813, 2022). "al. reported 39 lung cancer patients with EGFR mutations, out of which 38 were adenocarcinoma patients, and one patient had squamous cell carcinoma." (PMID 36613084, 2022). "The EGFR gene can undergo several mutations, particularly within exons 18–21, which encode a portion of the EGFR kinase domain that has been associated with some types of lung cancer." (PMID 35890400, 2022). "The EGFR mutation status in multiple lung cancers was evaluated to determine its therapeutic implications." (PMID 35740676, 2022).
lung cancer (continued). "A previous study in Japan has reported differential associations of soy consumption by EGFR lung cancer subtypes; the protective effect of soybean products was found only among EGFR mutated lung cancer." (PMID 36530673, 2022). "AKT1 has been identified as a candidate driver gene in adenocarcinoma and has been identified as an important regulator of invasion and metastasis of lung cancer cells having KRAS or EGFR mutations." (PMID 35932303, 2022). "Gefitinib and erlotinib are epidermal growth factor receptor (EGFR)-TKs inhibitors, recommended as the first-line therapy for EGFR-mutated lung cancer." (PMID 35804875, 2022). "For example, the identification of germline mutations in driver oncogenes like EGFR, has heightened interest in identifying germline mutations carrying a high inherited risk of lung cancer." (PMID 35596192, 2022). "The epidermal growth factor receptor (EGFR) gene-activating mutations represented the first molecular predictive biomarker which was discovered in lung cancer in 2004, underlying clinical responsiveness to the EGFR tyrosine kinase inhibitors (TKIs)." (PMID 36422186, 2022). "In this study, we have examined the EGFR gene mutation frequency of 864 different lung cancer patients in the surrounding area of the Qujing City of Yunnan Province by using the method of next-generation sequencing." (PMID 35606799, 2022). "Epidermal growth factor receptor (EGFR) mutation profiles play a vital role in treatment strategy decisions for non–small cell lung cancer (NSCLC)." (PMID 35800046, 2022). "Over the past decade, EGFR-TKI-targeted therapy had revolutionized the treatment landscape for advanced EGFR-mutated lung cancer patients." (PMID 36204237, 2022). "More than half of lung cancer patients have mutations in the epidermal growth factor receptor (EGFR)." (PMID 36077036, 2022). "Advances in understanding the relevance of EGFR mutations in lung cancer progression have led to the development of EGFR-targeted therapies." (PMID 35408753, 2022). "The mean survival time of patients with EGFR mutations was 2.58 and 3.51 years in the single lung cancer and LCF groups, respectively." (PMID 36233811, 2022). "Front-line EGFR tyrosine kinase inhibitor therapy is the standard therapy for patients with EGFR-mutated lung cancer." (PMID 35955669, 2022). "Among them, 57 resected tumors demonstrated primary lung cancer with EGFR mutations, which was confirmed by the Therascreen assay using tumor tissues." (PMID 35744511, 2022). "Next, Liu and co-authors introduces a simple SPR sensing platform for lung cancer diagnosis and used exosomes associated EGFR and programmed death ligand-1 (PD-L1) as biomarkers of disease." (PMID 35880114, 2022). "Overexpression of epidermal growth factor receptor (EGFR) has been well known to be implicated in the pathogenesis of lung cancer." (PMID 35326664, 2022). "Oncogenic mutations within the epidermal growth factor receptor (EGFR) tyrosine kinase domain (KD) are detected in 15 to 30% of all cases of non–small-cell lung cancers (NSCLCs)." (PMID 35867821, 2022). "Deletions of five amino acids from the β3/αC loop are most common in EGFR exon 19 variants in lung cancer." (PMID 36357385, 2022). "The NGS-based study detected EGFR variants in TKI-treated lung cancer tissue, suggesting that tumor-specific variants in ctDNA can be a monitoring marker of TKI treatment in NSCLC patients." (PMID 35892510, 2022). "cResistance to EGFR-TKIs remains a prominent problem that limits their clinical application for lung cancer patients with EGFR mutation." (PMID 36530971, 2022). "Same results were obtained in HCC827, another lung cancer cell line that carries a EGFR‐TKI–sensitizing mutation." (PMID 35593080, 2022).
lung cancer (continued). "For example, lung cancer bearing EGFR mutation, and colon cancer bearing KRAS mutation all benefit from inhibitors targeting mutation gene." (PMID 35155577, 2022). "It was noted that the types of EGFR gene mutation in the lung cancer patients of coal-producing areas were significantly different in other patients in Yunnan Province." (PMID 35606799, 2022). "In conclusion, dynamic monitoring STMs can help to predict the molecular features of EGFR‐mutated lung cancer during targeted therapy." (PMID 35543090, 2022). "The expression of interferon regulatory factor 1 (IRF1) was downregulated by the activation of EGFR signaling in EGFR-mutated non–small cell lung cancer." (PMID 35847084, 2022). "Many therapeutically actionable mutational drivers have been identified in this class of lung cancer, such as EGFR and ALK mutations, that allow for targeted therapies for these subsets of lung cancer patients." (PMID 35804837, 2022). "After acquiring resistance to EGFR-TKIs, EGFR-mutated lung cancer cells showed increased sensitivity to ferroptosis-inducing agents." (PMID 36712673, 2022). "Osimertinib is widely used for the treatment of advanced lung cancers harboring epidermal growth factor receptor (EGFR) mutations." (PMID 36081968, 2022). "Two mutations in EGFR, L858R and T790M, that are frequently observed in lung cancer patients, promoted binding to EphA2, and this binding was dependent on Ephexin1." (PMID 35668076, 2022). "CRISPR-Cas9 can be used to knock out the oncogenic mutant EGFR allele, which prevents the growth and proliferation of lung cancer cell lines and reduces tumor volumes in xenograft mice." (PMID 36135023, 2022). "The presence of EGFR variants in plasma DNA provides an ability to detect the EGFR variants and thus monitor the course of lung cancer treatment." (PMID 35892510, 2022). "In stage 1 patients with EGFR mutations, the single lung cancer group exhibited better survival than the LCF group." (PMID 36233811, 2022). "EGFR gene mutations and protein overexpression are associated with lung cancer, especially with NSCLC." (PMID 35053080, 2022). "In this study, among the 408 lung cancer patients with EGFR gene mutations in Eastern Yunnan, 87 types of EGFR gene mutation were observed." (PMID 35606799, 2022). "Clinicians can quickly obtain EGFR mutation results using this method when dealing with a patient newly diagnosed with lung cancer." (PMID 36142574, 2022). "Subsequent studies in EGFR mutated non‐small cell lung cancer confirmed that FASN-associated fatty acid metabolic pathway upregulation was the main principal for tyrosine kinase inhibitor (TKI)‐resistant EGFR mutated NSCLC growth." (PMID 35898882, 2022). "Our data revealed that MPE-derived lung cancer cell lines involves higher rates of EGFR mutations and fusion events compared to the lung adenocarcinoma-originated cell lines." (PMID 35428753, 2022). "Although small molecule tyrosine kinase inhibitors are effective in lung cancer driven by mutated EGFR, some receptor variants fail to respond." (PMID 36357385, 2022). "A study evaluated EGFR mutation status in 99 brain metastases from 51 patients with lung cancer, resulting in an AUC, accuracy, sensitivity, and specificity of 0.73, 78.6%, 81.3%, and 76.9%, respectively." (PMID 35734585, 2022). "More than 75% of non-small cell lung cancer (NSCLC) patients have multiple subclonal driver mutations, which affect the response of high-grade lung cancer to EGFR treatment." (PMID 35668934, 2022). "Our research provides further evidence demonstrating that the occurrence of lung cancer is closely related to the development of breast cancer, especially lung adenocarcinoma with EGFR mutation." (PMID 36313724, 2022). "In the present study, we evaluated the efficacy of pan-EGFR inhibitors in a panel of 15 lung cancer cell lines associated with the KRAS mutations phenotype." (PMID 35887120, 2022).